IL20RB (interleukin 20 receptor subunit beta)
Diseases named in the same sentence as IL20RB in open-access papers (continued):
Sharing a sentence is not in itself a finding about the gene and the disease.
glaucoma (3 papers, 2016 to 2022). Increased pressure in the eyeball due to obstruction of the outflow of aqueous humor. "In glaucoma patients with the IL-20RB mutation, the IL-20 family of cytokines would not bind efficiently to the IL-20RA/RB receptor so STAT3 would not be activated and translocated to the nucleus." (PMID 26903709, 2016). "In particular, our lab recently identified a T104M mutation in IL-20 receptor-B (IL-20RB) in primary open angle glaucoma patients from a large pedigree." (PMID 26903709, 2016). "Subsequently, many secondary downstream effects may contribute to the elevated intraocular pressure observed in glaucoma patients harboring the IL-20RB mutation and, ultimately, to glaucomatous damage." (PMID 26903709, 2016). "Based on these findings, this IL-20RB mutation is highly likely to impact the IL-20 signaling pathway, which may contribute to the pathogenesis of glaucoma in this family." (PMID 26903709, 2016). "The identification of a mutation in the IL-20RB gene in a glaucoma pedigree and changes in expression levels of IL-20 family members in the DBA/2J mouse suggest that disruption of normal IL-20 signaling in the eye may contribute to degenerative processes associated with glaucoma." (PMID 26903709, 2016). "While the IL-20RB mutation most likely is not a causative factor in the majority of glaucoma cases, the identification of this mutation has revealed that defective IL-20 signaling may lead to glaucoma in this large POAG pedigree." (PMID 26903709, 2016).
melanoma (3 papers, 2022 to 2025). A malignant, usually aggressive tumor composed of atypical, neoplastic melanocytes. "This evidence points to the potential role of IL20RB in inflammatory processes in melanoma, which warrants further investigation." (PMID 36553569, 2022).
prostate carcinoma (3 papers, 2015 to 2024). A carcinoma that arises from epithelial cells of the prostate gland. "IL20RB showed associations with phenotypes including prostate cancer, monocyte count, and carpal tunnel syndrome." (PMID 38903171, 2024).
autoimmune disease (2 papers, 2021 to 2025). A disorder resulting from loss of function or tissue destruction of an organ or multiple organs, arising from humoral or cellular immune responses of the individual to their own tissue constituents. "Several studies showed that Bcl2a, Birc5, and Il20rb were associated with chronic inflammation and autoimmune diseases, suggesting that inflammation could be one of the factors to drive the early capillary dropout." (PMID 40868180, 2025).
kidney cancer (2 papers, 2021 to 2022). Primary or metastatic malignant neoplasm involving the kidney. "At the same time, we estimated IL20RB expression in a wide range of cancer cell lines by CCLE database; results indicated that IL20RB was relatively highly expressed in kidney cancer cell lines." (PMID 35299868, 2022).
metastatic tumors (2 papers, 2022 to 2023). "Among the metastatic tumors, bone-tropic tumors expressed IL20RB at much higher levels than the tumors prone to metastasis to other organs." (PMID 36006737, 2022). "Notably, HMGA2 and IL20RB were more highly expressed in metastatic tumors than in primary tumors, consistent with the trend observed for GRIN2D expression." (PMID 37553583, 2023). "IL20RB was also upregulated in metastatic tumors more than in nonmetastatic tumors." (PMID 36006737, 2022).
Ureteral obstruction (2 papers, 2020 to 2021). Obstruction of the flow of urine through the ureter. "Localization of IL-20RB was determined in human biopsies and in the kidneys of mice that underwent unilateral ureteral obstruction (UUO)." (PMID 32306980, 2020).
acute kidney injury (1 paper, 2024). Sudden and sustained deterioration of the kidney function characterized by decreased glomerular filtration rate, increased serum creatinine or oliguria. "Our findings indicated that neutrophils and NETs play a key role in AAN and therapeutic targeting of PSTPIP2/NF-κB/IL-19/IL-20Rβ might extend novel strategies to minimize Aristolochic acid I-mediated acute kidney injury and apoptosis." (PMID 38314821, 2024).
allergic contact dermatitis (1 paper, 2019). An inflammatory skin condition caused by an immune response to direct contact between the skin and an allergen. "To assess their role in ACD, we set up a mouse model of PPD-induced allergic contact dermatitis and we showed that, in contrast to Il22-deficient mice, Il22ra1-, Il20rb- and Il24-deficient mice are partially protected against development of PPD-induced contact hypersensitivity." (PMID 30755657, 2019).
CNS demyelination diseases (1 paper, 2024). "Spinal cord IL-24 levels were also found to be significantly higher in wild-type mice than in IL-20RB−/− mice, suggesting that IL-24 plays a role in CNS demyelination diseases." (PMID 38737586, 2024).
diabetic nephropathy (1 paper, 2020). "IL-20RB was present in the renal biopsies of patients with lupus nephritis, IgA and diabetic nephropathy." (PMID 32306980, 2020).
epilepsy (1 paper, 2017). A brain disorder characterized by episodes of abnormally increased neuronal discharge resulting in transient episodes of sensory or motor neurological dysfunction, or psychic dysfunction. "All genes except for IL20RB, PPP2R2D and MZB1 were more expressed in the RNCC group as compared to the Idiopathic Epilepsy group." (PMID 28622332, 2017).
experimental autoimmune encephalomyelitis (1 paper, 2021). An autoimmune demyelinating disease of the central nervous system that is produced experimentally in animals by the injection of homogenized brain or spinal cord in Freund's adjuvant. "To address this hypothesis, we actively immunized IL-20RB–/– mice and wild-type mice to induce experimental autoimmune encephalomyelitis (EAE) and found that IL-20RB–/– mice showed amelioration of disease progression compared to wild-type mice." (PMID 34557075, 2021).
Hematochezia (1 paper, 2021). The passage of fresh (red) blood per anus, usually in or with stools. "We found that DSS treatment induced severe loss of body weight, diarrhea, hematochezia and deteriorating general condition with abdominal pain in both WT and Il20rb KO mice." (PMID 34078403, 2021).
IgA nephropathy (1 paper, 2020). "In summary, we showed the presence of IL-20RB in the kidneys of experimental animals, and also in kidney biopsy specimens of patients with diabetic and IgA nephropathy, or lupus nephritis." (PMID 32306980, 2020). "We found evident IL-20RB immunopositivity in tubular epithelial and glomerular cells of human kidney biopsies obtained from controls and patients with diabetic and IgA nephropathy or lupus nephritis." (PMID 32306980, 2020). "In the present study we demonstrated that IL-20RB is abundantly present on the epithelial and glomerular cells of patients with CKD of different aetiology, including diabetic and IgA nephropathy, or lupus nephritis." (PMID 32306980, 2020).
ischemic disease (1 paper, 2023). Lack of blood supply to an area of the body, resulting in impairment of tissue oxygenation. "Previous researchers have focused on the ability of IL-20 to act as a proinflammatory, chemotactic, and angiogenic cytokine in skin inflammation diseases, RA, liver fibrosis and ischemic diseases by activating its heterodimeric receptors (either IL-20RA/IL-20RB or IL-22RA1/IL-20RB)." (PMID 36835229, 2023).
oral candidiasis (1 paper, 2022). Infection of the mucosal lining of the mouth with the fungus Candida albicans. "To gain further evidence for the role of the IL-20 signaling pathway in the protection or exacerbation of acute oral candidiasis, we assessed tongue fungal burdens in IL20RB-deficient mice in OPC." (PMID 36225230, 2022). "The surprising finding that IL-20RB-deficient mice exhibited increased resistance to staphylococcal cutaneous infections, coupled with the downregulation of protective IL-17 responses, prompted us to ask whether this receptor might be playing a similar role in oral candidiasis." (PMID 36225230, 2022).
osteoporosis (1 paper, 2021). A condition of reduced bone mass, with decreased cortical thickness and a decrease in the number and size of the trabeculae of cancellous bone (but normal chemical composition), resulting in increased fracture incidence. "Our findings indicate that IL-20RB offers a potential therapeutic target for patients with bone loss disease and osteoporosis, which may effectively inhibit bone loss." (PMID 34122555, 2021).
renal fibrosis (1 paper, 2020). A final common manifestation of a wide variety of chronic kidney diseases characterized by glomerulosclerosis and tubulointerstitial fibrosis. "Investigating the underlying molecular mechanisms, we found a decreased expression of Tgfb1, Pdgfb and Ctgf, the core factors of renal fibrosis in the kidneys of Il20rb KO compared to WT mice after UUO." (PMID 32306980, 2020). "Furthermore, we defined a role of IL-20RB on the renal fibrosis in vivo." (PMID 32306980, 2020).
sarcoidosis (1 paper, 2024). Sarcoidosis is a multisystemic disorder of unknown cause characterized by the formation of immune granulomas in involved organs. "Our integrated model also demonstrated differential expression/methylation of IL20RB, ABCC11, SFSWAP, AGBL4, miR-146a-3p, and miR-378b between non-progressive and progressive sarcoidosis." (PMID 39080656, 2024).
tumor (31 papers, 2015 to 2026). "The top gene associated with LF2 was IL20RB, which we found to be epigenetically upregulated in ccRCC tumours." (PMID 39592856, 2024). "Increasing IL20RB expression associates tumor progression and poor prognosis in papillary RCC, and relates to poor survival for ccRCC patients." (PMID 37715154, 2023). "Consistent with IL22RA1, higher expression of IL10RB, IL10RA and IL20RB in tumor tissues was associated with worse survival in patients." (PMID 35874683, 2022). "Further clinical correlation analysis supports that IL20RB have positive relationship with characteristics that can reflect recurrence risk such as tumor stage and tumor grade." (PMID 35299868, 2022). "High IL20RB expression in ccRCC patients was associated with short overall survival, high tumor grade, and advanced TNM stage." (PMID 35883015, 2022). "Collectively, these data suggest that inhibition of STAT3 suppresses IL20RB-induced tumor proliferation in bone and reduces the risk of bone metastasis." (PMID 36006737, 2022). "Gene Ontology (GO) and Kyoto Encyclopedia of Genes and Genomes (KEGG) were undertaken, and the relationship between IL20RB and tumor immune infiltration was examined via single-sample GSEA (ssGSEA)." (PMID 41836171, 2026). "IL20RB expression levels correlated markedly with sample classification, lymph node status, tumor differentiation, and disease progression." (PMID 41836171, 2026). "Consistently, WB confirmed increased IL20RB protein expression in tumor tissues and across CRC cell lines." (PMID 41562081, 2025). "In NSCLC tumor samples and cell lines, IL-20RB and IL-22R1 are often overexpressed, while IL-20RA expression is suppressed, partly due to DNA CpG methylation and histone modifications." (PMID 40806452, 2025). "IL-24 binding to IL-20 receptor (IL-20R, composed of IL-20α/IL-22Rα and IL-20Rβ subunits) activates downstream signaling cascades leading to tumor cell apoptosis." (PMID 39782693, 2025). "Analysis of tumor growth dynamics and endpoint tumor weights provided additional evidence that IL20RB knockdown significantly hindered tumor development." (PMID 41562081, 2025). "In vivo bioluminescence imaging (IVIS) revealed markedly decreased signal intensity at tumor sites in the sh-IL20RB group, indicating reduced metabolic activity." (PMID 41562081, 2025). "Immunohistochemistry and semi-quantitative analysis further demonstrated a higher proportion of IL20RB-positive staining in tumor epithelium than in normal mucosa, supporting its potential involvement in colorectal tumorigenesis." (PMID 41562081, 2025). "By contrast, EtOH-treated Il20rb–/– PyMt tumors showed tumor growth kinetics similar to those of EtOH-treated WT PyMt tumors." (PMID 39782693, 2025). "We identified a relationship between BAP1 driver mutations and the epigenetic upregulation of EMT genes (IL20RB and WT1), correlating with increased tumour immune infiltration, advanced stage, and poorer patient survival." (PMID 39592856, 2024). "This relationship with metastasis was also found with WT1 (P = 0.017) and IL20RB (P = 7.4 × 10−06) expression in ccRCC tumours (Table EV7)." (PMID 39592856, 2024). "Tumor cells stimulate osteoclasts to release the ligand interleukin (IL)-19 for the IL receptor 20 subunit β (IL-20RB), which then triggers IL-20RB-expressing tumor cells to initiate downstream JAK1/STAT3 signaling." (PMID 39512767, 2024). "The in vivo study also confirmed that IL20RB knockdown combined with gemcitabine treatment further reduced tumor volume and weight." (PMID 38098005, 2023). "Immunofluorescence analysis of tissue sections showed that IL20RB expression was significantly elevated in tumor tissues compared with adjacent normal tissues, as well as in advanced stages versus early stages." (PMID 38098005, 2023). "During this process, tumor cells stimulate osteoclasts to release IL-19, which acts as the ligand for IL-20RB." (PMID 38260135, 2023).
tumor (continued). "The tumor formation rate was significantly lower in the IL20RB knockdown group than in the control group." (PMID 38098005, 2023). "Then, we explored the correlations between methylation and clinical characteristics; results suggest that the promoter methylation level of IL20RB in tumor tissues is significantly lower than that in normal tissues." (PMID 35299868, 2022). "Differential expression analysis revealed that the IL20RB expression level was notably higher in tumor samples than in normal samples." (PMID 35883015, 2022). "IL-20RB–promoted tumor proliferation in bone metastases was also diminished by Il19 KO of host mice." (PMID 36006737, 2022). "The results showed that IL20RB was overexpressed in tumor tissues and promoter methylation levels of IL20RB were downregulated in tumor tissues and the degree of decline became more obvious with the increase of stage and grade (p < 0.001)." (PMID 35883015, 2022). "Nevertheless, our study expands our understanding toward the roles of osteoclastic niches for tumor colonization in bone and, more importantly, reveals the potential of IL-20RB targeting with the neutralizing antibody in metastasis therapeutics." (PMID 36006737, 2022). "With the help of TIMER, we were able to find out the correlations between IL20RB expression and six immune cell types in the tumor microenvironment." (PMID 35299868, 2022). "The IL-19–neutralizing antibody effectively blocked osteoclast-induced STAT3 activation in IL20RB-expressing tumor cells." (PMID 36006737, 2022). "Firstly, we used UALCAN and GEPIA to explore the expression profile and prognostic value of IL20RB in various cancers; the expression profile in tumor cell lines was also analysed with CCLE and Expression Atlas." (PMID 35299868, 2022). "Primarily, we can conclude that the prognosis predicting ability of IL20RB is closely related with the tumor immune microenvironment in ccRCC." (PMID 35299868, 2022). "The box plot and Kaplan-Meier curve again confirmed that IL20RB expression level was higher in tumor tissues and patients with overexpressed IL20RB had shorter overall survival (OS) (p = 0.013)." (PMID 35883015, 2022). "Quantitative Real-time PCR (qRT-PCR) and western blots were used to validate the expression levels of IL20RB in tumor cells." (PMID 35883015, 2022). "The online database UALCAN further validated that the expression and methylation levels of IL20RB were different between kidney normal and tumor tissues." (PMID 35883015, 2022). "The analysis revealed a significant elevation of IL20RB expression in tumor tissues compared with that in the paratumor normal tissues of the same patients." (PMID 36006737, 2022). "Results show that the prognosis predicting ability of IL20RB proves intimately related with tumor immune microenvironment." (PMID 35299868, 2022). "IL20RB expression significantly enhanced organoid growth of human and murine tumor cells with the treatment of osteoclastic CM." (PMID 36006737, 2022). "Although the IL(R)-based signature exhibited powerful predictive ability, these signature members themselves (IL-7R, IL-5RA, IL-20RB, IL-11, and IL-22RA1) were rarely reported to be used to predict tumor prognosis." (PMID 34497605, 2021). "We observed that IDO1, IL20RB, PPP3CA, and PLAU were negatively associated with favorable outcomes and were found to participate in tumor progression, whereas ESR2 showed the opposite effect." (PMID 33718118, 2020). "IL20RB expression in tumor specimens was detected through immunohistochemistry (IHC)." (PMID 41836171, 2026). "IL20RB expression levels in tumor cells were confirmed via Western blot analysis." (PMID 41836171, 2026). "In addition, IL-20RB overexpression upregulated the mRNA levels of several tumor stemness markers, including transcriptional factors such as NANOG, SOX2, and POU5F1, while IL-20RB knockdown downregulated their mRNA levels." (PMID 40806452, 2025).